CEP128 (centrosomal protein 128)
Description:
Is involved in the negative regulation of ciliogenesis and plays a role in spermatogenesis. Contributes to the regulation of the TGFB/BMP signaling pathway at the primary cilium, where it is required for ciliary localization of RAB11A, likely affecting the trafficking and regulation of TGFB/BMP pathway components. Required, together with ODF2, for the formation of the subdistal appendage of the centriole (By similarity).
Synonyms: C14orf145; C14orf61; LEDP/132
Tractability: PROTAC: ubiquitination databases record sites on it.
Gene: Protein-coding gene on chromosome 14 (80,476,969 to 80,959,517, reverse strand). Ensembl gene ENSG00000100629.
Subcellular location: Cytoplasm, cytoskeleton, microtubule organizing center, centrosome, centriole; Cytoplasm, cytoskeleton, cilium basal body; Cytoplasm, cytoskeleton, microtubule organizing center, centrosome; Cytoplasm, cytoskeleton, spindle pole
Subcellular location (Human Protein Atlas): Centrosome
Gene Ontology:
Biological process: intracellular protein localization; motile cilium assembly; negative regulation of cilium assembly; positive regulation of protein localization; regulation of gene expression; regulation of transforming growth factor beta receptor signaling pathway; sperm flagellum assembly
Cellular component: centriolar subdistal appendage; centriole; centrosome; ciliary basal body; sperm head-tail coupling apparatus; spindle pole
Genetic constraint (gnomAD): Loss-of-function variants: 67 observed, 85.81 expected, observed/expected ratio (o/e) 0.78, 90% interval 0.64 to 0.96. The upper end of that interval is the gene's LOEUF score, 0.96, which puts it in group 4 of 6, group 1 being the genes least tolerant of losing a copy. Missense variants: 820 observed, 866.1 expected, observed/expected ratio (o/e) 0.95, 90% interval 0.89 to 1. Synonymous variants: 310 observed, 307.49 expected, observed/expected ratio (o/e) 1.01, 90% interval 0.92 to 1.11.
Homologues: Orthologues: chimpanzee CEP128 (99% identical), macaque CEP128 (97% identical), rabbit CEP128 (88% identical), pig CEP128 (86% identical), dog CEP128 (85% identical), rat Cep128 (79% identical), mouse Cep128 (79% identical), guinea pig CEP128 (69% identical), tropical clawed frog cep128 (45% identical).
Diseases named in the same sentence as CEP128 in open-access papers:
CEP128 is named in the same sentence as 12 diseases in open-access papers, as found by Europe PMC text mining. Sharing a sentence is not in itself a finding about the gene and the disease. The quoted sentences say what the papers report.
bladder cancer (7 papers, 2018 to 2024). "The circRNA-SHPRH was shown to be a promising biomarker in CRC progression, whereas the circ-CEP128 was correlated with bladder cancer." (PMID 38891888, 2024). "Centrosomal protein of 128 kDa (CEP128) plays a role in bladder cancer and autoimmune thyroid disease." (PMID 36299731, 2022). "miR-145 is regulated by another circRNA CEP128 which can activate MAPK signaling pathway in bladder cancer." (PMID 34168984, 2021).
autoimmune thyroid disease (2 papers, 2020 to 2022). Inflammatory disease of the thyroid gland due to autoimmune responses leading to lymphocytic infiltration of the gland. "A recent study reported an association between polymorphisms in CEP128 and autoimmune thyroid disease in humans, although the mechanism underlying this association is unclear." (PMID 32631225, 2020).
infertile (2 papers, 2022). "Detecting pathogenic mutations of CEP128 in unrelated infertile patients would provide strong evidence to confirm the causative role of CEP128 deficiency in human spermatogenesis." (PMID 35296684, 2022). "In this study, we identified a homozygous missense variant of CEP128 in two siblings with infertility characterized by an extremely low sperm count and complete sperm morphological anomalies." (PMID 35296684, 2022). "Collectively, these findings suggest that the homozygous missense variant p.R222Q in CEP128 might contribute to the sperm defects in the two infertile patients." (PMID 35296684, 2022).
diffuse large B-cell lymphoma (1 paper, 2019). "Mutations within CEP128 have been associated with an aggressive type of lymphoma, the diffuse large B-cell lymphoma (DLBCL)." (PMID 30606113, 2019).
glioma (1 paper, 2022). A benign or malignant brain and spinal cord tumor that arises from glial cells (astrocytes, oligodendrocytes, ependymal cells). "For example, in glioma tissues and cell lines, circRNA CEP128 expression was upregulated, and circRNA CEP128 expression was higher in temozolomide-resistant glioma cells than in their parental cells." (PMID 35615158, 2022). "In addition, miR-145-5p was expressed at low levels in glioma cells and temozolomide-resistant glioma cells, and miR-145-5p was also identified as a target of circRNA CEP128." (PMID 35615158, 2022).
male infertility (1 paper, 2022). The inability of the male to effect fertilization of an ovum after a specified period of unprotected intercourse. "In this study, a homozygous missense variant of CEP128 was identified in two siblings with primary male infertility related to cryptozoospermia from a consanguineous family through whole-exome sequencing." (PMID 35296684, 2022). "Moreover, Cep128 knock-out mice manifest male infertility associated with disrupted sperm quality." (PMID 35296684, 2022). "Therefore, the proteomics approach, RNA-sequencing and phosphoproteomics analysis were employed on mice testes to elucidate the potential mechanism of CEP128 involvement in male infertility." (PMID 35296684, 2022).
cancer (4 papers, 2017 to 2020). A tumor composed of atypical neoplastic, often pleomorphic cells that invade other tissues. "Centrosomal protein 128 (CEP128) is part of the centrosomal protein family, including CEP55 that has been implicated in cancer progression." (PMID 30606113, 2019). "Further, five genes, ALMS1, TRAPPC9, CEP128, OR10T2, and CPVL, are among the SCLC genes but not in any of the common cancer gene lists, yet these genes were mutated in M9." (PMID 29050228, 2017).
CEP128 also shares sentences with these, for which no sentence is quoted: congenital heart disease (1 paper); hyperthyroidism (1); immune thrombocytopenia (1); lymphoma (1); thyroid disorders (1).